GPX4 (glutathione peroxidase 4)
Diseases named in the same sentence as GPX4 in open-access papers (continued):
Sharing a sentence is not in itself a finding about the gene and the disease.
tumor (continued). "However, the drug resistance of cancer cells was significantly reduced while downregulating the expression of GPx4, suggesting that GPx4 may reduce the sensitivity of cancer cells to radiotherapy and chemotherapy by regulating the intracellular oxidation level of tumour cells." (PMID 36923926, 2023). "Meanwhile, western blot to detect ferroptosis‐associated markers of degrasyn‐treated HepG2 cells and xenograft tumor samples showed that key markers of ferroptosis, SLC7A11, and GPX4 decreased obviously." (PMID 37492786, 2023). "Combining GPX4 inhibitors with immunotherapy can further activate T cells in the TME, subsequently enhancing their killing effect on tumor cells." (PMID 37064872, 2023). "Ferroptosis markers was closely related with clinical characteristics; ferroptosis score based on GPX4, NOX1, and FACL4 can effectively reflect CRC prognosis, tumor progression and ACT responsiveness with high C‐index." (PMID 35855531, 2023). "SXC, GPX4, and FSP1 are highly expressed in tumors and are related to the poor prognosis of patients, suggesting that tumor cells tend to inhibit their ferroptosis." (PMID 37064872, 2023). "Double knockdown of GPX4 and GPD2 synergistically inhibited tumor growth by exacerbating ferroptosis in vitro and in vivo." (PMID 37739961, 2023). "A positive feedback loop between SLC43A2 and NFκB signaling pathway regulated ferroptosis and tumor progression via controlling the GSH content and GPX4 expression." (PMID 37268653, 2023). "Immunofluorescence assays showed that GPX4 knockdown increased CD8+ T-cell infiltration, and flow cytometry of subcutaneous tumor tissue confirmed this result." (PMID 37649598, 2023). "In vivo, pharmacodynamic studies revealed that IONP@PTX significantly inhibited tumor volume in GBM xenografts and decreased the expression level of GPX4 protein in tumor tissues." (PMID 36910646, 2023). "Currently, in related research examining ferroptosis after SAH, the primary research focuses on the GSH/GPX4, NADPH/FSP1/COQ, and other pathways; however, the Hippo/YAP pathway has exhibited good anti-ferroptosis in tumor-related research." (PMID 37266433, 2023). "In vivo, knockdown of TRIM26 inhibited, while GPX4 re-expression restored, GBM intracranial tumor growth, which in turn altered the overall survival of tumor-bearing mice." (PMID 37872147, 2023). "Compared to that in peritumor tissues, the expression of ferroptosis-inducing genes, including PTGS2, ALOX12, TFR2, and HMOX1, was decreased in tumor tissues, whereas ferroptosis-suppressor genes, including SLC7A11 and GPX4, were increased." (PMID 37554285, 2023). "After verifying the therapeutic effect of ZPG@H in vivo, the expression of GPX4 and SLC7A11 in tumor tissues suffering from ferroptosis was examined using IHC staining." (PMID 37206228, 2023). "Matrine can considerably decrease the GSH content and the expression of GPX4 and SLC7A1 to inhibit the proliferation of tumor cells." (PMID 37833746, 2023). "Ferroptosis can be promoted using system Xc-inhibitors, GPX4 inhibitors, GSH synthesis inhibitors, and lipid peroxidation stimulants, which will stop tumor growth." (PMID 37598126, 2023). "It has been shown that high level of lncRNA PVT1 directly interacts with miR-214-3p, hindering adsorption of GPX4, increasing GPX4 content and maintaining GSH in a reduced state, which inhibits ferroptosis and promotes tumor cell proliferation." (PMID 37313458, 2023). "Pharmacologic inhibitors of xCT (either SLC7A11 or GPX4) induce ferroptosis of NSCLC cells and other tumor types." (PMID 37381723, 2023). "FOXA2 deletion contributed to tumor suppression and chemoresistance in CRC by inducing ferroptosis via the Nrf2/GPX4 signaling suppression." (PMID 37875418, 2023). "In our research, GPX4 expression was negatively correlated with the survival of CRC patients, which demonstrated the tumor inhibition effect of ferroptosis in CRC." (PMID 37346068, 2023).
tumor (continued). "Taken together, these results suggest that Escin inhibits tumor growth in vivo and in vitro via regulating the ferroptosis mediated by G6PD/GPX4 axis." (PMID 37149513, 2023). "The tumor growth was decreased after the application of PTW, and the analysis of the cytotoxic response revealed a reduction of glutathione peroxidase 4 (GPX4) and Glutathione (GSH)." (PMID 35954398, 2022). "We also investigated the expression of GPX4, 4-HNE, GOT1, NCOA4, FTH, and LC3B in tumor tissues using IHC staining." (PMID 36387145, 2022). "Remarkably, GPx4 increases following ADRB2 blockers treatment in cultured cells and in vivo, in tumor xenografts of 786-O cells from mice treated with propranolol or ICI compared with vehicle treatment." (PMID 35163250, 2022). "After degradation in tumor cells, it would release ML210, effectively inhibiting the activity of GPX4 and activating the ferroptosis pathway." (PMID 36274142, 2022). "Based on these deductions, we here knock down five additional genes related to iron and redox homeostasis (NRF2, GPX4, SLC7A11, FSP1, FTH1), for further improving the anti-tumor efficacy of GIFT." (PMID 36329436, 2022). "Current research shows that 5-ALA induces ferroptosis through glutathione peroxidase 4 (GPX4) and HMOX1, and has an anti-tumor effect in ESCC." (PMID 36237575, 2022). "In tumor cells, SLC7A11-mediated cystine uptake promotes GPX4 protein synthesis to reduce sensitivity to ferroptotic cell death." (PMID 36138043, 2022). "PCBMA promoted the accumulation of Fe3O4@PCBMA in tumor lesions, while SIM inhibited the expression of HMGCR, thereby downregulating mevalonate pathway and GPX4 expression, and inducing ferroptosis." (PMID 36467032, 2022). "Immunohistochemical staining showed relative expression of GPX4, xCT, MTTP and ki67 in tumor tissues from ob/ob mice." (PMID 35978266, 2022). "We here develop a novel cancer therapy named Ferroptosis ASsassinates Tumor (FAST) by combining iron oxide nanoparticles with cancer-selective knockdown of seven key ferroptosis-resistant genes (FPN, LCN2, FTH1, FSP1, GPX4, SLC7A11, NRF2)." (PMID 36329436, 2022). "CircIL4R directly sponges microRNA-541-3p, and inhibition of miR-541-3p mitigated the effects of circIL4R knockdown on HCC cells; this suggests that circIL4R served as a tumor promoter and ferroptosis inhibitor in HCC by the miR-541-3p/GPX4 network." (PMID 35663406, 2022). "The results of immunohistochemical staining showed that the expression levels of KI67, GPX4, SLC7A11, and TET1 in the tumor tissues of NOD-scd mice injected with Atranorin@SPION were significantly lower than those in the control group." (PMID 36237989, 2022). "Compared with normal tissues, CASP6, GPX4, NOD2, and WNK1 were upregulated in HCC samples, presenting low- to medium-intensity expressions, and high expression of CYCS emerged in tumor tissues." (PMID 35368686, 2022). "Immunohistochemical staining showed relatively expression of GPX4, xCT, MTTP and ki67 in tumor tissues from ob/ob mice than in those from C57 mice, and these changes were inhibited by treatment with L‐OHP and recovered by injecting adipocyte exosomes." (PMID 35978266, 2022). "It was found that the expressions of GPX4 and FTH1 in A549 xenograft tumours were significantly reduced by irradiation, which was reversed by the upregulation of ANGPTL4." (PMID 36050447, 2022). "A tumor-targeted MOF nanosheet system with multienzyme-like catalytic activity can inhibit the antiferroptotic mechanism mediated by GPX4 and FSP1 in tumor cells, thus enhancing ferroptotic damage." (PMID 36467032, 2022). "Immunohistochemical staining revealed that Punicalin treatment significantly downregulated GPX4, PSTK and Ki-67 activities in tumor samples." (PMID 34983546, 2022). "As previously observed in mRNA expression level, CASP4, GPX4, IL18, NLRP1, and IRF1 were upregulated in tumor samples, whereas PLCG1 was downregulated." (PMID 35000541, 2022).
tumor (continued). "It has recently been demonstrated that GPX4 activity is mediated by DHODH and that brequinar suppresses tumor growth of GPX4lo cells by inducing ferroptosis." (PMID 35943801, 2022). "CHMP2B, CHMP6, and RIPK3 were downregulated, while CXCL1, GPX4, and TRAF2 were upregulated in tumor samples." (PMID 36046241, 2022). "However, tumor cells can adapt to the microenvironment through metabolic change; some small molecules, such as the ferroptosis inducers, that merely increase the concentration of ROS in tumor cells or inhibit the activity of GPX4 cannot achieve strong and lasting antitumor effects." (PMID 34987385, 2021). "High intracellular GSH/GPX4 levels in GBM cells lead to epithelial–mesenchymal transition, which results in tumor progression, metastasis and chemoresistance." (PMID 33917880, 2021). "Additionally, two major ferroptosis-inducing factors, erastin and RSL3, prevented tumor growth in a xenograft mouse tumor model, and sensitivity profiling of 117 cancer cell lines showed that diffuse large B-cell lymphoma and renal cell carcinoma were highly sensitive to GPX4-modulated ferroptosis." (PMID 34502181, 2021). "The level of GPX4 was reduced, and EGR1 was increased in tumor for 13-treated group compared with vehicle group." (PMID 33472669, 2021). "These NPs reduce the growth of tumor cells (HT-1080, MCF-7 and HCT-116) in vitro and downregulate the enzymatic activity of GPX4." (PMID 34834199, 2021). "This suggested that GPX4 and AIFM2 played important roles in regulating tumor immunity by affecting the ferroptosis of B cell, CD8+ T cell, and CD4+ T cell in HNSC." (PMID 34722530, 2021). "In total, 5 of the 34 pyroptosis-related genes were related to prognosis and four of them (ELANE, GPX4, GSDMD, and TIRAP) had different expression values between tumor and normal tissues, which were, thus, chosen as prognostic DEPRGs." (PMID 34722500, 2021). "AMSN dissolution in tumor cells releases manganese, allowing for GSH depletion and inducing FERR by inhibiting GPX4 activity." (PMID 34834199, 2021). "Nanoparticle (NP) platforms offer an unmatched potential for tumor-targeting simultaneous delivery of PS, exogenous iron and small GSH/GPX4 reduction molecule." (PMID 34238297, 2021). "Inhibiting ferroptosis by manipulating essential regulatory genes, such as GPX4 and ACSL4, curtailed GBM aggressiveness and prolonged the survival of tumor-bearing mice." (PMID 33110073, 2020). "Suppressing ferroptosis by manipulating key ferroptosis regulators in tumor cells, such as GPX4 and acyl-CoA synthetase long chain family member 4 (ACSL4), reduces necrosis and dampens tumor aggressiveness." (PMID 33110073, 2020). "Both GPX4 and TMEM173 mRNA expression was upregulated in the PDAC tumor group compared to the normal group." (PMID 33311482, 2020). "In vitro, celecoxib (PTGS2 inhibitor) or exogenous prostaglandin E2 (PGE2, an enzymatic product of PTGS2) failed to affect the growth of Gpx4−/− PDAC cells, indicating that the PTGS2 pathway may not be important for tumor growth associated with GPX4 depletion (Supplementary 3g)." (PMID 33311482, 2020). "GPx4 suppresses formation and progression of HCC by inhibition of angiogenesis and tumor cell proliferation as well as by immune-mediated mechanisms." (PMID 29515790, 2018). "GPx4-overexpressing HCC-3 derived tumors grew slower as compared to vector transfected cells and exhibited reduced final tumor weight." (PMID 29515790, 2018). "GPx4 overexpression (~3-fold) did not raise maximal or specific muscle force generation in LLC-tumour-bearing mice." (PMID 41854231, 2026).
tumor (continued). "In the acidic tumor microenvironment, CMSP releases Cu+ ions that catalyze ROS generation via Fenton-like reactions, as well as sorafenib, which inhibits System Xc− to deplete GSH and suppress GPX4 activity." (PMID 41476754, 2026). "However, their combined efficacy is constrained by the tumor microenvironment (TME), where elevated levels of glutathione (GSH) and glutathione peroxidase 4 (GPX4) effectively mitigate reactive oxygen species (ROS) and lipid peroxidation." (PMID 41476754, 2026). "Muscle mitochondrial respiration was reduced in wildtype tumour-bearing mice by ~40% when compared to control mice but not altered in tumour-bearing GPx4 Tg mice." (PMID 41854231, 2026). "In addition, treatment with the GPX4 inhibitor RSL3 can induce DCs dysfunction, while knockout of PPARG can reverse this dysfunction and maintain their anti‐tumor effect." (PMID 41560416, 2026). "Specifically, we found that GPX4 is serotonylated by TGM2 at residues Gln55 and Gln77, which increases GPX4 protein stability by attenuating its ubiquitin-mediated degradation, thereby conferring resistance to ferroptosis and facilitating tumor growth." (PMID 42049702, 2026). "DMF inhibits GPX4 activity by reducing the GSH/GSSG ratio and forms a positive feedback loop with 5-LOX, which synergistically increases lipid peroxidation levels by 3–5 times and significantly induces tumor cell death." (PMID 40535125, 2025). "Furthermore, several studies have shown that combining GPX4 inhibition with EGFR blockade (e.g., cetuximab) or PI3K-AKT pathway inhibitors results in synergistic ferroptosis and tumor regression." (PMID 40650229, 2025). "The authors further showed that GPX4 inhibition in vivo led to the reprogramming of the tumour microenvironment and increased the infiltration of CD8+ T cells and M1 macrophages that exert anti-tumour effects." (PMID 40136651, 2025). "Additionally, during pre-invasive stages, tumor cells enhance local ROS clearance by upregulating antioxidant enzymes like SOD2 and GPX4, which aid in evading immune surveillance and enhance metastatic potential." (PMID 40563367, 2025). "Unlike liver cancer cells, tumor-infiltrating immune cells overexpress GPX-4 but not FSP1, so iFSP1 selectively induces ferroptosis in cancer cells but not immune cells." (PMID 40169575, 2025). "Additionally, IHC analysis revealed that TFR levels were increased and Ki67, GPX4, and SLC7A11 levels were decreased in shROCK2-R-QBC-939 tumours." (PMID 40615369, 2025). "Promising local administration mechanisms have been developed for RSL380, but the current lack of systemic effect renders RSL3 and other GPX4 inhibitors ineffective for targeting metastases or difficult-to-access tumor sites for the moment." (PMID 40957885, 2025). "The suppressive role of CAP on GPX4, FSP1 and SLC7A11 were confirmed using mice tumor samples." (PMID 39781456, 2025). "Furthermore, GPX4 is elevated in malignant tumors compared to benign specimens and negatively correlated with TSPO expression in clinical tumor specimens." (PMID 40842566, 2025). "By down-regulating glutathione peroxidase 4 (GPX4), the platform synergizes with IFN-γ-induced ferroptotic signaling to intensify tumor-cell lethality, establishing a positive-feedback loop between immune activation and regulated cell death that amplifies antitumor efficacy." (PMID 41209565, 2025). "Through the frequency of keywords, we found that “prognosis,” “autophagy,” “gpx4,” “immunotherapy,” “oxidative stress,” “incRNA,” “biomarker,” “lipid peroxidation,” “NFR2,” “temozolomide treatment,” “tumor microenvironment” and other keywords appeared most frequently." (PMID 40822852, 2025). "Both GPX4 and FSP1 are key contributors to tumor resistance, especially GPX4." (PMID 39935430, 2025). "The results showed that GPX4 expression primarily influences macrophage infiltration within the tumor, but not in the stroma." (PMID 40365295, 2025).
tumor (continued). "Both in vitro and in vivo results demonstrated that the Mn-S1N3/SAE significantly enhanced catalytic activity within the tumor microenvironment (TME), triggered tumor ferroptosis via LPO accumulation and GPX4 inactivation, which achieved greater tumor suppression than the Mn-N4/SAE analogue." (PMID 41215762, 2025). "Therefore, developing a tumor-specific nanoparticle vector for RSL3, which targets GPX4 in NSCLC, is feasible." (PMID 40191731, 2025). "Studies have shown that GPX4 and SLC7A11 are central factors in suppressing lipid peroxidation; their high expression significantly enhances the antioxidant capacity of tumor cells, enabling them to evade ferroptosis induced by immunotherapy, chemotherapy, or radiotherapy." (PMID 40416987, 2025). "Nevertheless, in tumor cells, Keap1 inactivation leads to an increase in the stability and activity of NRF2, subsequently activating numerous target genes involved in GPX4–GSH-mediated ferroptosis defense, including SLC7A11, thereby facilitating the protection of cancer cells from ferroptosis." (PMID 40136417, 2025). "Finally, immunohistochemical analysis of xenograft tumor tissues showed that MWDT treatment in vivo reduced the expression of PTK2B, p-STAT3, and GPX4, confirming the inhibition of this signaling pathway within the tumor microenvironment." (PMID 41166024, 2025). "Additionally, the pH‐responsive and photothermal properties of MIL‐Cu1.8S‐TPP/FA facilitated the controlled release of iron and copper ions, triggering ferroptosis and cuproptosis via GSH depletion, GPX4 inactivation, and FDX‐1 downregulation in tumor cells." (PMID 40558386, 2025). "The combined inhibition of ALK plus inhibition of activated bypass signals plus inhibition of GPX4 may be a potent therapeutic strategy for patients with ALK+ NSCLC to prevent the development of resistance to ALK‐TKIs and lead to tumor eradication." (PMID 39369284, 2025). "Furthermore, immunostaining of tumor samples, including MHCC97H xenografts and PDXs, showed a considerable decrease in GPX4 expression following IR treatment in cases where USP14 was deleted or inhibited in vivo." (PMID 40595451, 2025). "The GPX4-knockdown metM-Wntlung cells, relative to scramble controls, produced lower metastatic tumor burden regardless of ferrostatin-1 pretreatment." (PMID 40001204, 2025). "Furthermore, analysis of protein expression in tumor tissues revealed that evodiamine consistently inhibited the expression of TRIM26 and GPX4 proteins, aligning with the in vitro findings." (PMID 40420092, 2025). "This dual mechanism triggers a self-reinforcing therapeutic cycle: ferroptosis releases tumor antigens, activating CD8+ T cells to secrete interferon-γ (IFN-γ), which suppresses GPX4 expression and exacerbates lipid peroxidation, thereby sustaining ferroptotic cell death." (PMID 40846966, 2025). "To inform our choice of ICI for testing the effect of GPX4 knockdown plus ICI treatment on TNBC progression in vivo, we used aggregated published human data of tumor GPX4 expression, ICI treatment, and overall survival from female patients in the online resource KMPlotter." (PMID 40001204, 2025). "A study of melanoma showed that tumor growth was suppressed in mice with a Treg-specific deletion of GPX4 but antitumor immune responses were enhanced without inducing autoimmunity." (PMID 40083691, 2025). "Using various pharmacological inhibitors for ferroptosis suppressors, the authors were able to show that targeting GPX4, that catalyses the oxidation of GSH to GSSG, through the inhibitor RSL3 led to much greater cell death in LAR tumours compared to other TNBC subtypes." (PMID 40136651, 2025). "Importantly, this dependency creates a therapeutic vulnerability: pharmacological inhibition of antioxidant components—such as GPX4, Trx1, TrxR, and SOD1—can tip the balance toward lethal oxidative stress and selectively kill tumor cells." (PMID 40867898, 2025).